IL1B (interleukin 1 beta)
Diseases named in the same sentence as IL1B in open-access papers (continued):
Sharing a sentence is not in itself a finding about the gene and the disease.
infection (continued). "In addition, as expected, in IRE1α knockdown cells GSK abolished the inhibitory effect of SubABwt on STEC O113 ΔsubAB infection-induced IL-1β release." (PMID 35345462, 2022). "Other studies have found that in germ-free zebrafish, Lactobacillus casei BL23 in could effectively promote the expression of pro-inflammatory factors such as TNF-α, IL-10 and IL-1β to fight the infection with Aeromonas veronii." (PMID 35700135, 2022). "In this study, we confirmed that the phosphorylation of IκBα and p65 and the transcription of pro-IL-1β were more highly induced by ASFV-ΔH240R infection than ASFV-WT, indicating that NF-κB signaling and inflammasome activation were induced in the ASFV-ΔH240R-infected PAMs." (PMID 36326277, 2022). "Additionally, ELISA showed that the levels of secreted pro-inflammatory cytokines IL-1β and IL-6 were significantly increased in the mice of the ‘Scald + Infection’ group compared with those of the ‘Sham + Infection’ group." (PMID 34898366, 2022). "Interestingly, the infection of chickens with C. jejuni significantly upregulated (P < 0.05) the expression of the IL-10 (2.7 fold), IL-17A (2.9 fold), IL-1β (1.9 fold), IFN-γ (1.5 fold), and CXCLI1 (1.8 fold) genes compared to NC group." (PMID 36135600, 2022). "In a human monocyte (THP-1) cell infection model, MtbΔ2159 showed reduced uptake and intracellular survival and increased expression of pro-inflammatory molecules, including IL-1β, IP-10, and MIP-1α, compared to the wild type M. tuberculosis and Rv2159c-complemented MtbΔ2159 strains." (PMID 35745538, 2022). "We showed here that ASFV-ΔH240R infection induced a strong mature IL-1β response." (PMID 36326277, 2022). "Infection of airway epithelial cells by SARS-CoV-2 causes cytological damage by activating the local immune response, releasing proinflammatory mediators such as IFNγ, IL-1β, IL-6, TNF-α." (PMID 36012968, 2022). "Three upregulated cytokines, il-1b (18.09 ± 0.7539-fold change), il-6 (49.40 ± 1.641-fold change), and tnf-a (79.59 ± 6.921-fold change), indicated significant pulmonary inflammation levels post infection." (PMID 36249423, 2022). "Furthermore, increased IL-1β release was also observed in human peripheral blood-derived monocytes (PBMCs)-differentiated macrophages upon EV-A71 infection." (PMID 36503883, 2022). "In this study, we proved that SVA infection induces IL-1β secretion in macrophages and pigs." (PMID 35254168, 2022). "The study further examined different key immune genes such as the transcript level of tumor necrosis factor-alpha (TNFα), interleukin-6 (IL-6), interleukin-8 (IL-8), interleukin-10 (IL-10), interleukin-1 beta (IL-1β), and transforming growth factor-beta 1 (TGFβ1) during the early phase of infection." (PMID 36145441, 2022). "Additionally, numerous studies have shown that the NLRP3 inflammasome is involved in cellular inflammatory responses and helps to recognize pathogen infection, thereby promoting the maturation of IL-1β and IL-18 in macrophages." (PMID 36430657, 2022). "IL-1β recruits macrophages, monocytes, and neutrophils to sites of infection." (PMID 35077922, 2022). "In addition to IL-6, CXCL1 and CCL2, IL-1β protein levels in PGRN KO kidney were also significantly lower than WT mice at day 9 post-infection when significantly lower fungal burden was observed in PGRN KO mice." (PMID 36121866, 2022). "Here, infection with the wild-type ME49 strain promoted IL-1β in THP-1 cells." (PMID 35626667, 2022). "Therefore, in summary, stimulation of THP-1 with P. acnes leads to the expression of active caspase-1(p10) and IL-1β in an infection-dependent manner." (PMID 35871079, 2022). "Moreover, it has not been elucidated that the relationship between the phenotype with reduced ASFV-ΔH240R replication and IL-1β production in ASFV-ΔH240R infection." (PMID 36326277, 2022).
infection (continued). "Active inflammasomes also regulate gasdermin D activation resulting in pore formation and IL-1β release in the context of pyroptosis, which might account for the membrane damage we observed in monocytes after 2 h infection." (PMID 35509315, 2022). "To test how the mutations on M2 would impact the ability of the virus to induce IL-1β because of NLRP3 activation, we conducted an NLRP3 reconstitution assay followed by infection as well as PAMs infection with the respective virus and measured the production of IL-1β." (PMID 35062292, 2022). "Nevertheless, an excessive level of IL-1β upon infection by various viruses may lead to various inflammatory diseases, including hepatitis and encephalitis." (PMID 36559293, 2022). "Furthermore, more virulent strains of HSV-1 cause more severe corneal pathology that is associated with increased IL-1β and IL-18 levels, and IL-18 contributes to HSV-2 pathology in a genital model of infection." (PMID 35038917, 2022). "New research finds that mice lacking caspase-1 are more susceptible to Francisella compared to mice lacking IL-1β and IL-18, suggesting cell death itself and other caspase-1-dependent pathways help restrict infection." (PMID 36189207, 2022). "Released IL-1B recruits immune cells to the site of infection/injury." (PMID 35663964, 2022). "Our data clearly demonstrated that PE_PGRS19 caused macrophage pyroptosis leading to the release of pro-inflammatory cytokines, and the pretreatment of macrophages with the pyroptosis inhibitor NSA blocked the increased transcript levels of il-6, il-1β, and il-18 induced by Ms_PE_PGRS19 infection." (PMID 36557726, 2022). "However, infection with the MDV/RB1B strain resulted in persistently high levels of IL-1β transcription in both the spleen and bursa." (PMID 36680047, 2022). "Specifically, IL-1β and IL-6 expression was significantly increased at 1 dpi, and IL-6 sustained the high expression level up to 3 dpi, which suggests that IL-1β plays a crucial role in the response to infection by Zika virus as well as other flaviviruses, WNV and JEV." (PMID 36069671, 2022). "Herein, reduced IL-1β secretion and pyroptosis observed in Casp8/RIPK3−/− mice are possible mechanisms that may contribute to increased susceptibility to infection." (PMID 36532444, 2022). "IL-1β and IL-18 are interleukins belonging to the IL-1 family and are produced as a response to cellular insults that range from infection, such as the classically described LPS-induced inflammasome activation, to metabolic imbalances resulting in ionic fluxes through cell membrane." (PMID 36361818, 2022). "During infection, there is an increase in IL-1β and IL-8 mRNA in the umbilical vein." (PMID 35213550, 2022). "Interleukin-1 released in early stage of infection as pro-inflammatory cytokines that regulates both types of immunity (innate and acquired stage); IL-1β was the most potent and fastest genes in humoral immunity that stimulate the inflammation and trigger the immunity." (PMID 35822445, 2022). "Interestingly, our previous results showed that IL-1β was induced in response to L. corymbifera during the early and late stages of the infection." (PMID 36311802, 2022). "However, NLRP3-deficient mice also display significant lung damage following infection and reduced IL-1β production." (PMID 36580480, 2022). "Interestingly, IL-1β mRNA levels were significantly lower at 60 days post infection compared to 30 days post infection." (PMID 36189368, 2022). "Moreover, it rapidly reduced the expression of IL-10 in the later stage with the decline of IL-1β, IL-6, TNF-α, and IFN-γ, to prevent the continuously excessive release of IL-10 from causing severe immune suppression and uncontrollable infection." (PMID 35071595, 2022).
infection (continued). "This infection is generally characterized by inflammatory cytokines interleukin-1 beta (IL-1β), tumor necrotizing factor alpha (TNF-α), interleukin-6 (IL-6), chemokine (CX-C motif) ligand 2 (CXCL2), and IL-8 (also known as chemokine (CX-C motif) ligand 8-CXCL8)." (PMID 35053737, 2022). "To study the effects of SubAB on inflammasome activation, we first investigated whether SubAB affects IL-1β and IL-18 production during infection of macrophages with STEC O113:H21." (PMID 35345462, 2022). "Immunohistochemical staining of IL‐1β in the naïve and UPEC‐infected bladder further showed that bladder epithelial cells may be the dominant producer of IL‐1β post‐infection." (PMID 35018740, 2022). "The activation of the pyroptosis route has been demonstrated by studying two proteins associated with the inflammasome, i.e., pyrin domain containing 3 (NLRP3) and IL-1β, after infections in mice and murine macrophages with A. hydrophila and A. veronii, respectively." (PMID 35874671, 2022). "Similarly, E. coli 1587 infection stimulated upregulation of IL-1β, IL-6, IL-10, and TNF-α mRNA transcription levels in mouse colons at 3 dpi, but this phenomenon mostly diminished in 7 dpi except for IL-6." (PMID 35643532, 2022). "Formation of inflammasomes is induced upon a variety of stimuli, including PAMPs derived from infection and DAMPs derived from host damage, which culminate in the maturation of pro-inflammatory cytokines, such as interleukin (IL)-1β and IL-18, that activate host immunity." (PMID 36387275, 2022). "Although the increased proportion of macrophages did not depend on GSDMD in both spleen and peritoneal lavage fluid (PLF), deficiency of GSDMD caused the minor release of the pro-inflammatory cytokines interleukin-1β (IL-1β) and interleukin-18 (IL-18) during the infection in vivo." (PMID 36311722, 2022). "However, one mechanism employed by the inflammasome to protect against intratracheal infection is NLRP3/ASC secretion of IL-1β and IL-18." (PMID 35626718, 2022). "The activation of NLRP3 inflammasome is not the only source of IL-1β in vivo, so blocking the IL-1 signal increases risk of infection." (PMID 35252186, 2022). "However, the levels of pro-IL-1β mRNA and IL-1β protein decreased to a certain extent after infection." (PMID 35409050, 2022). "Using randomly selected clinical isolates to infect THP-1 macrophages (five from early infections and five from chronic infections), we then measured mRNA levels of IL-1β, TNF, IL-8, and IL-10 through quantitative reverse transcription polymerase chain reaction (qRT-PCR) analysis." (PMID 33664232, 2021). "Our recent studies observed that active vitamin D enhanced hBD-2 in Salmonella-infected IECs to protect the host against infection, while it downregulated proinflammatory responses (IL-8 & IL-1β) to prevent the host from the detrimental effects of overwhelming inflammation." (PMID 34576700, 2021). "In addition, infection with P. gingivalis also up-regulates the ROS/NF-κB p65 signaling pathway, leading to the expression of IL-1β and TNF-α." (PMID 34831265, 2021). "Upregulation of IL-1β early during infection might indicate an additional role in signaling at this stage in addition to leukocyte trafficking." (PMID 35046947, 2021). "infection increased the levels of il1b and tnf mRNA in the ME/Arc." (PMID 34587172, 2021). "These alterations were accompanied with the elevated transcriptional level of 10 innate immune genes with infection time, where il-1b, il-6, il-8, and il-10 exhibited a higher expression at 33°C than at 18°C and was attenuated by exogenous myo-inositol in both groups." (PMID 34566956, 2021). "As a consequence, MΦs are activated and attracted by IL-1β production to the site of infection." (PMID 33815401, 2021). "The expression of IL-1β and IL-18 mRNA in the three infection groups was higher than that in the control group at 6 and 9 h post-infection (P < 0.01), with the highest expression at 9 h post-infection." (PMID 33678162, 2021).
infection (continued). "Something worth pointing out in this work is the fact that IL-1β, IL-6, and H2O2 increased their secretions during the entire ten weeks of infection and, although IL-1β decreased in the fourth week, it maintained higher concentrations as opposed to those in the non-inoculated control mice." (PMID 34358055, 2021). "Would the release of IL-1β from renal epithelial cells just aggravate the infection?" (PMID 34944029, 2021). "Likewise, ISG15 is an unconventional secreted alarmin, and its release at the site of infection contributes to the recruitment of DCs that produce IL-1β and enhance local production of IFN-γ." (PMID 34670268, 2021). "We also measured Tnfa, Il1b, Il6 and Isg15 expression and found that macrophages infected with plasmid-cured R. equi (33701-) had reduced expression of Tnfa at 8h, and of Il6 at both 4- and 8h after infection." (PMID 34473814, 2021). "To test this, we infected LPS-primed human macrophage-like THP1 cells with S. Typhi mutants and assayed for pyroptotic cell death with lactate dehydrogenase (LDH) release and IL-1β release at 2 hours post-infection as well as cell death kinetics using SYTOX Green staining over 10 hours of infection." (PMID 33651854, 2021). "Additionally, T. denticola has been shown to degrade IL-1β and IL-6, and infection of both P. gingivalis and T. denticola synergistically stimulated the production of IL-6 by macrophage-like cells." (PMID 34079525, 2021). "Taken together, these results indicated that the NLRP3 pathway was activated during H2 infection and significantly involved in cell death and, especially, IL-1β release, however, the activation of NLRP3 accounted only partly for the overall cell death induced by H2." (PMID 34009097, 2021). "Treatment of trophoblast cells with cytokines, such as interleukin (IL)-1β and IL-6, elicited similar responses indicating that infection may alter placental nutrient uptake and fetal transfer." (PMID 34394055, 2021). "Additionally, at 2 weeks PC, the level of either IL-1β or IL-6 was un-influenced by post-infection immunotherapy, when compared to controls." (PMID 34777338, 2021). "Both GM-CSF and albGM-CSF exposure enhanced IL-1β secretion from BMDMs after overnight infection." (PMID 32382128, 2021). "Pro-inflammatory cytokines, such as IL-1β, IL-6, and TNF-α, released by tumor itself or immune cells following infection or tissue injury caused by chemotherapy, surgery, or radiation can signal to the CNS, leading to symptoms of distressing fatigue and other behavioral changes." (PMID 34122094, 2021). "However, the IL-1β mRNA expression in trachea was downregulated in group IV compared with IL-1β mRNA expression in group I from day 1 to 5 post-infection (p < 0.05) and compared with level in group II (p < 0.01) at day 7 post-infection." (PMID 34988139, 2021). "While IL-1β induces the growth and proliferation of T and B lymphocytes and macrophages, IL-8 has chemotactic capacity and attracts neutrophils to the site of possible infection." (PMID 34944352, 2021). "In addition, BAL IL-1β levels were significantly higher in mice that received the 040417 treatment compared with controls in the first hours post-infection." (PMID 34207076, 2021). "Although inflammatory factors can produce adaptive behavioral response and promote energy conservation to fight infection or recover from injury, excessive proinflammatory factors (such as TNF-α and IL-1β) will cause damage to the body and cause inflammation-related diseases." (PMID 34630124, 2021). "IL-1β was originally identified as a pro-inflammatory cytokine, capable of inducing local and systemic inflammation as well as a fever response reaction in response to infection or injury." (PMID 34122073, 2021). "IFN-γ, TNF-α, IL-1β, and IL-6 can promote inflammation when tissue injury or infection occurs." (PMID 33564301, 2021).
infection (continued). "Since C. difficile is primarily a gastro-intestinal (GI) pathogen and the effects were observed in bone marrow and blood, our data suggests that IL-1β is a key intermediate in the communication between gut and bone marrow to control infection-induced neutrophilia." (PMID 33718269, 2021). "In line with this, we found that the number of PAKflic CFU was higher than that of PAK at 6 hours after infection, which might explain higher IL-1β and TNFα in BALF of PAKflic infected mice as compared to mice infected with PAK." (PMID 33793661, 2021). "In addition, activation of inflammasome and transcription of IL-1β by modified vaccinia virus Ankara (MVA) infection is dependent on the crosstalk between TLR2-MyD88 and the NLRP3." (PMID 34638790, 2021). "In addition, we found a sustained upregulation of multiple inflammatory transcripts in iron-loaded FthΔ/Δ mice as early as 12 hours after infection and the resultant massive overproduction of the key proinflammatory cytokines IL-1β, IL-6, and TNF-α." (PMID 34236052, 2021). "Following infection, an early influx with a high number of hyperactivated neutrophils releasing high levels of IL-1β, ROS, and NETs may augment infection and disease." (PMID 34073501, 2021). "High and significant (p < 0.05) upregulation of IL-1β was also observed at early stages of infection in both tissues in the Immersion group compared to those in NVC control fish, suggesting a proactive inflammatory response in the immunized fish for combating the virus." (PMID 34925332, 2021). "The mRNA levels of interleukin 1β (IL1β) and tumor necrosis factor alpha (TNFα) in the liver of WT-infected mice were significantly higher than those in the liver of ΔspvB-infected mice at 3 days post-infection." (PMID 33475464, 2021). "The early release of IL-1β is important for recruitment of neutrophils, but prolonged IL-1β release also has pathological consequences as IL-1β recruits more neutrophils to infection sites and inflammasome activation leads to immflammatory pyroptotic macrophage cell death." (PMID 33571211, 2021). "Despite M2 markers, the infection of these macrophages with Mtb demonstrated an atypical profile of response, with poor control of infection and similar release of immune mediators, such as IL-10, IL-1β, and TNF-α." (PMID 33921194, 2021). "In addition, our study showed that transcript abundance of cd4 (Th1 response), cd209 (innate immune response), ccr7 (Th2), and il1b (inflammation) were suppressed during the infection with sea lice alone." (PMID 35046944, 2021). "Similarly, our study showed that NLRP6 mediates the secretion of IL-1β and IL-6 during macrophages infection with S. pneumoniae." (PMID 33918100, 2021). "Moreover, NLRC5 knockdown significantly reduced the IL-1β secretion of human myeloid cells and primary monocytes during infection." (PMID 34307322, 2021). "As cytokines, such as IFN-γ and IL-1β, can contribute to “innate memory” or trained immunity, future studies should investigate the relationship of these plasma cytokines, both at baseline and after infection or immunization, on measures of trained immunity." (PMID 34597920, 2021). "Caspase-1−/− and Asc−/− BMDMs in contrast showed significantly reduced IL-1β levels upon infection, indicating that NLRP3 inflammasome components (ASC) and targets (caspase-1) function upstream of GSDMD and have a potential dual role in cell death and release of pro-inflammatory cytokines." (PMID 34718331, 2021). "Intrigued by our finding of a sharp delineation of pathogen-induced mitochondrial cell death and cytokine release in our ex vivo infection model, we assessed whether IL-1β and IL-18 levels correlate with severity of disease in TB patients." (PMID 34718331, 2021). "Hence, the relationship between the PGE2 and IL-1β cannot be expected to be the same in various infection models and warrants further investigation." (PMID 34319170, 2021).